MIR1285-1 (microRNA 1285-1)
Synonyms: hsa-mir-1285-1; MIRN1285-1
Gene: MicroRNA gene on chromosome 7 (92,204,015 to 92,204,098, reverse strand). Ensembl gene ENSG00000221520.
Homologues: Orthologues: chimpanzee ptr-mir-1285 (100% identical).